KIF21B (kinesin family member 21B)
Diseases named in the same sentence as KIF21B in open-access papers (continued):
Sharing a sentence is not in itself a finding about the gene and the disease.
microcephaly (1 paper, 2020). A congenital or acquired developmental disorder in which the circumference of the head is smaller than normal for the person's age and sex. "We demonstrate, in vivo, that the expression of KIF21B missense variants specifically recapitulates patients’ neurodevelopmental abnormalities, including microcephaly and reduced intra- and inter-hemispheric connectivity." (PMID 32415109, 2020). "Expression of the KIF21B p.Gln313Lys variant recapitulates the microcephaly phenotype observed in the reported subject." (PMID 32415109, 2020). "Here, the authors show that KIF21B variants in humans associate with corpus callosum agenesis and microcephaly." (PMID 32415109, 2020). "We report three missense variants and one duplication in KIF21B in individuals with neurodevelopmental disorders associated with brain malformations, including corpus callosum agenesis (ACC) and microcephaly." (PMID 32415109, 2020). "Given that introduction of the p.Ala1001Thr variant that is expected to attenuate KIF21B autoinhibition at the same extent as the p.Gln313Lys substitution variant, but does not reduce brain size in zebrafish, the hyperactivation of KIF21B is unlikely to be driving the phenotype of microcephaly." (PMID 32415109, 2020).
mucinous adenocarcinoma (1 paper, 2022). An invasive adenocarcinoma composed of malignant glandular cells which contain intracytoplasmic mucin. "Based on the histological subtype of COAD, the expression of KIF21B was also increased expression in adenocarcinoma (n = 243)/mucinous adenocarcinoma (n = 37) compared to normal tissues (n = 43) from UALCAN database." (PMID 36451772, 2022).
prostate carcinoma (1 paper, 2020). A carcinoma that arises from epithelial cells of the prostate gland. "KIF21B encodes a member of the kinesin superfamily and was reported to be significantly associated with poor prognosis of prostate cancer patients." (PMID 32087735, 2020).
small cell lung carcinoma (1 paper, 2020). Small cell lung cancer (SCLC) is a highly aggressive malignant neoplasm, accounting for 10-15% of lung cancer cases, characterized byrapid growth, and early metastasis. "KIF21B showed a significant positive correlation with 23 CAGs enriched in many cancer-related pathways such as thyroid cancer, small cell lung cancer and central carbon metabolism in cancer, suggesting that KIF21B plays a role in the development of various types of cancer." (PMID 31896739, 2020).
uveitis (1 paper, 2022). An inflammatory process affecting a part of or the entire uvea. "Genes associated with the risk of developing uveitis include ERAP1, intergenic region 2p15, IL23R, IL10-IL19, IL18R1-IL1R1, IL6R, KIF21B, and EYS." (PMID 35629038, 2022).
tumor (10 papers, 2019 to 2025). "To explore the effect of KIF21B on the development of OS, we then compared the expression levels of KIF21B between tumor tissue, junction tissue and bone tissue." (PMID 33585227, 2020). "KIF21B is a potential oncogene that resists the induction of apoptosis and facilitates malignant tumorigenesis, tumor development, intrusion, and metastasis." (PMID 32848739, 2020). "Results showed that the tumor size and weight of KIF21B-silenced group were significantly lower than those of control group." (PMID 32536821, 2020). "The results showed that the expression of KIF21B in the tumor tissues was significantly higher than that in the junction and bone tissues." (PMID 33585227, 2020). "High KIF21B expression at the tumor site was also confirmed by western blotting analysis and qRT-PCR." (PMID 33585227, 2020). "In addition, KIF21B was elevated expression in tumor specimens (n = 275) compared with normal specimens (n = 349) from GEPIA database." (PMID 36451772, 2022). "Moreover, KIF21B was also significant overexpression in primary tumor specimens compared with normal group based on the sample type in COAD." (PMID 36451772, 2022). "Compared with the control, KIF21B reduced the tumor size and weight." (PMID 33585227, 2020). "The results demonstrated that knocking down KIF21B in 143B and U2-OS cells could increase cell apoptosis, inhibit cell proliferation, and reduce tumor formation in nude mice." (PMID 33585227, 2020). "The effect of KIF21B on tumor growth in vivo was examined using nude mice model." (PMID 32536821, 2020). "The mRNA expression of seven PRAN genes (CCL14, CPA3, CX3CR1, IKZF3, KIF21B, LINC00528, and SLC16A4) showed significant differences between normal and tumor samples in the advanced NSCLC cohort." (PMID 38728242, 2024). "The mRNA expression of seven PRAN genes (CCL14, CPA3, CX3CR1, IKZF3, KIF21B, LINC00528, and SLC16A4) exhibited noticeable difference between normal and tumor in NSCLC." (PMID 38728242, 2024). "Our data demonstrated that silencing of KIF21B decreased the migration and invasion of H1299 and A549 cells, but not BEAS-2B cells, suggesting the potential role of KIF21B in modulation of tumor metastasis." (PMID 32536821, 2020). "Since the PI3K/AKT pathway is widely involved in tumor development, we further studied the changes in the key proteins of the PI3K/AKT pathway after silencing KIF21B." (PMID 33585227, 2020). "Since the effects of KIF21B on NSCLC cells had been revealed by in vitro experiments, we further investigate its effect on tumor growth in vivo." (PMID 32536821, 2020). "KIF21B, a kinesin motor protein, is upregulated in multiple cancers and enhances proliferation, migration, and survival via anti-apoptotic effects and PI3K/Akt pathway activation, while in certain contexts it also modulates Wnt/β-catenin signaling and antagonizes tumor-suppressive microRNAs." (PMID 41403951, 2025).
cancer (8 papers, 2014 to 2025). A tumor composed of atypical neoplastic, often pleomorphic cells that invade other tissues. "Next, to better understand the expression correlation and underlying mechanisms of KIF21B in cancer, we analyzed the functional status of KIF21B in diversity cancers from the CancerSEA database." (PMID 36451772, 2022). "Additionally, we showed that kif21b is also expressed in activated astrocytes Abundant levels of kif21b expression have been linked to a poorer prognosis of several forms of cancers." (PMID 25274010, 2014). "Heatmap results showed that NRP1, MFAP2, KLC1, DST, and MYOZ3 were generally downregulated in cancer cell lines, while KIF21B, SRI, INCENP, and KEAP1 were also downregulated." (PMID 40228435, 2025). "Further validation in four independent cohorts showed that KEAP1, SRI, MFAP1, MFAP2, INCENP, and KIF21B were consistently upregulated in cancer tissues, while MYOZ3, DST, and TIAM1 were consistently downregulated." (PMID 40228435, 2025). "The functional state of KIF21B in various types of cancers was conducted by single-cell RNA-sequencing." (PMID 36451772, 2022). "The other five genes (i.e. PPP1R15A, MOSPD2, FAM84B, GARS, KIF21B) have demonstrated involvement in the progression of various cancers." (PMID 32087735, 2020). "Given the critical role of the Akt signaling pathway involved in the growth, metastasis and apoptosis of cancer cells, the effect of KIF21B on this signaling pathway was evaluated." (PMID 32536821, 2020). "The correlation between KIF21B and cancer immune infiltrates was analyzed by TIMER." (PMID 36451772, 2022). "Additionally, KIF21B was positively correlated with CD4+ T cell and neutrophil cell, which involved in regulation of immune infiltrate of cancer cells." (PMID 36451772, 2022). "Moreover, other genes from diverse functional groups appeared in our analysis, such as signal transducers promoting cancer growth (CD53, RAB33A, GNA11, CANX, OCRL, GIPC1, and SOS1), microtubule formation (KIF21B) and cell migration (ASAP2)." (PMID 29535628, 2018).
neurodegenerative disease (4 papers, 2014 to 2020). A disorder of the central nervous system characterized by gradual and progressive loss of neural tissue and neurologic function. "An increase in expression of KIF21B was connected to accelerated progression of neurodegenerative diseases, and microduplications of the locus bearing the KIF21B gene were linked to neurodevelopmental abnormalities." (PMID 28290984, 2017). "A kinesin known as KIF21B is found in several types of cells including neurons and immune cells and genetic alterations in this protein have been linked with several neurodegenerative diseases." (PMID 28290984, 2017). "High levels of kif21b expression in neurodegenerative diseases are associated with a more rapid disease course as we have shown here, again pointing to an important role of kif21b in astrocytes." (PMID 25274010, 2014). "We hypothesized that kif21b is aberrantly expressed in neurodegenerative disease and that its expression is associated with disease progression." (PMID 25274010, 2014).
neurodevelopmental disorder (3 papers, 2020 to 2023). A behavioral and cognitive disorder with onset during the developmental period that involves impaired or aberrant development of intellectual, motor, or social functions. "Mutations in Kif21b have been shown to impair neuronal migration, axonal growth and branching, leading to neurodevelopmental disorders." (PMID 37862092, 2023). "Here we provide the evidence of a causal relationship between variants in KIF21B and neurodevelopmental disorders." (PMID 32415109, 2020). "Interestingly, peripheral LPS exposure led to downregulation of some genes such as Kcnj9 and Kif21b, the deficiency of which has been associated with the occurrence of neurological and neurodevelopmental disorders, again highlighting the importance of the immune system-brain axis." (PMID 36040311, 2022). "Altogether, our data indicate that impaired KIF21B autoregulation and function play a critical role in the pathogenicity of human neurodevelopmental disorder." (PMID 32415109, 2020).
neurological disorder (1 paper, 2026). "Mutations in KIF1A (resulting in KIF1-associated neurological disorder/KAND), KIF1B (resulting in Charcot-Marie-Tooth disease), KIF5A (resulting in ALS), and KIF21B (causing neurodevelopmental disorders) result in various neurological disorders where intracellular transport defects are evident." (PMID 41277110, 2026).
KIF21B also shares sentences with these, for which no sentence is quoted: ulcerative colitis (2 papers); adenocarcinoma (1); amyotrophic lateral sclerosis (1); autism spectrum disorder (1); Autoimmunity (1); benign gliomas (1); bipolar disorder (1); cerebral artery occlusion (1); glioblastoma multiforme (1); Huntington disease (1); Intellectual disability (1); Neurodevelopmental delay (1); oral cancer (1); T-cell acute lymphoblastic leukemia (1); thyroid cancer (1).